NEAT1 (nuclear paraspeckle assembly transcript 1)
Diseases named in the same sentence as NEAT1 in open-access papers (continued):
Sharing a sentence is not in itself a finding about the gene and the disease.
breast cancer (continued). "High levels of NEAT1, miR-21, and RRM2 have been observed in different breast cancer cell lines, and their elevated levels correlate with poor clinical outcomes, suggesting that the NEAT1/miR-21-RRM2 signaling axis contributes to breast cancer development." (PMID 34527584, 2021). "For example, NEAT1 was reported to serve as a ceRNA of ZEB1, which competes with miR-448 in breast cancer." (PMID 33987091, 2021). "It has been reported that with the down-regulation of NEAT1, the expression of CBX7 protein in breast cancer cells is also significantly down-regulated (p < 0.01)." (PMID 34659360, 2021). "In breast cancer, multiple lncRNAs played an important role in the regulation of TRAIL, like HOTAIR, NEAT1, BCAR4 and DSCAM-AS1." (PMID 34282054, 2021). "Comparing breast cancer with fibroadenoma patients, HOTAIR expression levels were significantly higher, whereas NEAT1 expression levels were significantly lower in the breast cancer patients than in the fibroadenoma patients at p < 0.0001." (PMID 33670447, 2021). "It has been determined that the protein level of CBX7 is positively correlated with NEAT1 in breast cancer cells, proving that CBX7 is indeed a target gene regulated by NEAT1." (PMID 34659360, 2021). "The biological functions of NEAT1 and SNHG16 are rarely investigated in breast cancer and our findings provided a novel direction in the field of cancer-related lncRNAs for future research." (PMID 33494814, 2021). "Serum HOTAIR level was found to be positively correlated with NEAT1 and MALAT1 levels in the breast cancer patients (r = 0.35, p < 0.05 and r = 0.51, p < 0.001, respectively)." (PMID 33670447, 2021). "Univariate and multivariate logistic regression analyses were carried out to assess the predictive values of PVT1, MALAT1, NEAT1, HOTAIR, PAI-1, and OPN in breast cancer." (PMID 33670447, 2021). "Surprisingly, we found that eNEMAL regulates NEAT1 expression by modulating levels of the short and long isoforms in MCF7 breast cancer cells." (PMID 34019552, 2021). "A relatively well studied lncRNA transcript Nuclear Enriched Abundant Transcript 1 (NEAT1) has been found to promote proliferation and epithelial to mesenchymal transition (EMT) pathways in breast cancer." (PMID 33126510, 2020). "Previous reports demonstrated that lncRNA nuclear-enriched abundant transcript 1 (NEAT1) was involved in the development of diverse human cancers, including myeloma, breast cancer and cervical cancer." (PMID 32414769, 2020). "In agreement with previous reports, our analysis also showed that NEAT1 and MALAT1 were enriched in ER+ breast cancers." (PMID 32244924, 2020). "NEAT1 which promotes EMT and proliferation in breast cancer, additionally promotes migration and invasion in endometrial cancer through regulation of the miR-144-3p/EZH2 axis." (PMID 33126510, 2020). "RUNX1 was recently shown to regulate lncRNAs NEAT1 and MALAT1, which have critical roles in the onset and progression of breast cancer." (PMID 32655837, 2020). "Among these genes, two were non-coding, MALAT1 and NEAT1, of which both are connected to CSC properties in several cancer types, including breast cancer." (PMID 31191614, 2019). "They showed the implication on lncRNA in the four subtypes of breast cancer, that is, (a) basal‐like, (b) HER2+, (c) luminal A, and (d) luminal B. NEAT1 was one of three lncRNA—besides OPI5‐AS1 and AC008124.1—involved in all four subtypes." (PMID 30430751, 2019). "NEAT1 overexpression promotes EMT and invasion in breast cancer, renal cell carcinoma, renal cell carcinoma, hepatoblastoma and nasopharyngeal carcinoma." (PMID 30374364, 2018). "Nuclear paraspeckle assembly transcript 1 (NEAT1) is a nuclear-restricted lncRNA, which is dysregulated in various human cancers, including leukemia, bladder cancer, lung cancer, breast cancer and gastric cancer." (PMID 28212646, 2017).
breast cancer (continued). "Given variable genetic and epigenetic alterations among these breast cancer cell lines, we predicted that some cell lines had lost the BRCA1/NEAT1/miR-129- 5p regulation axis." (PMID 27556296, 2016). "Moreover, HyPR-MS maps prostate cancer complexes (MALAT1/NEAT1/NORAD), while TOBAP-MS identifies HULC’s 140 interactors in liver cancer, and BioID-MS links HOTAIR to ribosomes in breast cancer cell lines." (PMID 40861865, 2025). "Indeed, these “hubs” included several lncRNAs well known for their role in breast cancer, e.g., MALAT1 at rank 17, SNHG29 at rank 2, SNHG16 at rank 19, GAS5 at rank 1, XIST at rank 11, NEAT1 at rank 23, NORAD and others." (PMID 38838009, 2024). "NEAT1 participates in many critical biological processes and acts as a potential predictor or target for prognosis in CRC, lung cancer, gastric cancer, and breast cancer." (PMID 36262350, 2022). "For example, NEAT1 induced breast cancer progression by regulating the miR-410-3p/CCND1 axis, indicating that NEAT1 may be a potential therapeutic target in breast cancer." (PMID 34956895, 2021). "Studies found that tumor development was related to the aberrant expression of lncRNAs, and lncRNA nuclear paraspeckle assembly transcript 1 (lncRNA NEAT1) was upregulated in a variety of tumor tissues, including breast cancer, hepatocellular carcinoma, and lung cancer." (PMID 34837887, 2021). "In contrast, the expression levels of HOTAIR and NEAT1 were not significantly altered in breast cancer patients." (PMID 33670447, 2021). "Furthermore, NEAT1 and MALAT1, lncRNAs often deregulated in breast cancer, were also occupied by RUNX1 both in interphase and mitosis." (PMID 32655837, 2020). "It has been revealed that there were significant up regulations of MALAT1, SRA, and NEAT1, while significant GAS5 down regulation in Iranian breast cancer samples which were taken from younger (< 45 years) and older (> 45 years) cases compared with normal tissues." (PMID 31956395, 2020). "Zhang et al17 reported NEAT1 promotes proliferation and EMT in breast cancer." (PMID 30575330, 2019). "To better understand the shared impact of lncRNAs and miRNAs in the regulatory post‐transcriptional network, we focused here on the relationships between (a) lncRNA H19 and miR‐675, (b) NEAT1 and miR‐204, and (c) HOTAIR and miR‐331 in plasma of early breast cancer (BC) patients." (PMID 30803129, 2019). "Additionally, NEAT1 physically interacts with FUS, promoting cell growth in breast cancer." (PMID 39715205, 2024). "The results showed that five lncRNAs including HOTAIR, DANCR, PVT1, LINC00511, and NEAT1 and 16 miRNAs and five of their targets—VEGFA, BTG2, E2F3, IRAK1, and SMAD4—have significantly different expression patterns in normal individuals compared to those with breast cancer." (PMID 36726376, 2023). "Additionally, the downregulation of NEAT1 induced the expression of N-cadherin and vimentin, but repressed that of E-cadherin, indicating that NEAT1 may inhibit the EMT process in breast cancer cells." (PMID 36613528, 2022). "NEAT1 has been shown to be involved in many cancers, and promotes chemoresistance in TNBC, while early studies on the lncRNA CYTOR (also known as LINC00152) have shown it may regulate signalling in breast cancers." (PMID 34681087, 2021). "In addition, NEAT1 could increase the expression of high mobility group AT-hook 2 (HMGA2) by sponging miR-211, thereby enhancing the invasiveness of breast cancer cells." (PMID 34527584, 2021). "Nuclear paraspeckle assembly transcript 1 (NEAT1), transcribed from the endocrine neoplasia type 1 locus on chromosome 11, has been discovered as essential regulators of oncogenesis in multiple human tumors, such as prostate cancer, breast cancer and hepatocellular carcinoma." (PMID 32336952, 2020).
breast cancer (continued). "Each of the three players in NEAT1/miR-133b/TIMM17A axis may become a novel therapeutic target for the treatment of breast cancer, which is of crucial significance for the clinical prevention and diagnosis of breast cancer." (PMID 31344855, 2019). "Other studies showed that Neat1 may increase proliferation, invasion, Endothelial-to-Mesenchymal-Transition (EMT), and chemo-resistance in multiple cancer types including lung cancer, breast cancer and in renal-cell carcinoma." (PMID 29312630, 2017). "The discovery of the BRCA1/NEAT1/miR-129-5p/WNT4 axis and the pivotal roles of WNT4 in WNT signaling activation as well as in the enhancement of BCSC generation suggest that WNT signaling is a potential therapeutic target for breast cancer with alterations in this signaling axis." (PMID 27556296, 2016). "Erik Knutsen and colleagues conducted a study, they discovered that a noticeable correlation was observed in relation to the expression level of NEAT1-2 and the grade of breast cancer tumors, as well as the presence of human epidermal growth factor receptor 2 (HER2)-positive BC samples." (PMID 40110044, 2025). "The same study reported higher expression of NEAT1 in estrogen receptor positive (ER+) breast cancers, when compared to estrogen-receptor-negative- (ER-) BC." (PMID 36139550, 2022). "In addition, competing with other miRNAs (miR34a-5p, miR204-5p) NEAT1 also controls the expression of ACSL4, essential for ER-negative breast cancer progression; while competing with miR124 it form a positive loop including STAT3 to promote breast cancer progression." (PMID 36182907, 2022). "Also, HOTAIR, NEAT1, PAI-1, and OPN could discriminate between breast cancer and fibroadenoma." (PMID 33670447, 2021). "However, NEAT1 was not a predictor of metastasis-free survival in breast cancer." (PMID 33987091, 2021). "In addition, a group of researchers detected the serum levels of lncRNAs PVT1, HOTAIR, NEAT1, and MALAT1 from Egyptian breast cancer and fibroadenoma patients, as well as healthy donors, and found that serum PVT1, HOTAIR, and NEAT1 could serve as potential biomarkers for breast cancer." (PMID 38505593, 2024). "In the present study, we aim to investigate the expression levels of NEAT1, LINC00299, and CASC2 genes in breast cancer samples compared to adjacent nonmalignant samples, as well as their relationship with the spliced XBP1 mRNA level." (PMID 37706018, 2023). "It is noteworthy that NEAT1 was decreased and SNHG16 was increased in breast cancer samples with MIR3613 deletion compared to the non-deletion group from TCGA breast cancer cohort." (PMID 33494814, 2021). "Notably, mir-612, which is expressed from the same region of the 3′ end of the long isoform of NEAT1 and in the same direction, is one of the most abundant spliceosomal miRNAs in the MCF-10A normal breast cell line, but is not found among the spliceosomal miRNAs of the breast cancer cells." (PMID 37624034, 2023).
glioma (136 papers, 2016 to 2025). A benign or malignant brain and spinal cord tumor that arises from glial cells (astrocytes, oligodendrocytes, ependymal cells). "Another extensively studied lncRNA, NEAT1 (nuclear-enriched abundant transcript 1), functions within nuclear paraspeckles and has been associated with glioma cell viability, invasion, and therapeutic responses." (PMID 40076844, 2025). "Given the multifaceted function of NEAT1 in gene regulation at the transcriptional and posttranscriptional levels, molecular mechanisms underlying such glioma transcriptomic changes remain elusive." (PMID 39032650, 2024). "Patients diagnosed with stage III–IV gliomas exhibiting heightened NEAT1 expression are associated with unfavorable prognostic outcomes." (PMID 39453684, 2024). "The glioma risk factor RBP QKI drew our attention because multiple consensus QREs are found immediately upstream of the human NEAT1 PAS." (PMID 39032650, 2024). "The findings revealed that recurrent glioma exhibited the highest levels of NEAT1 expression, suggesting a potential association between NEAT1 and glioma prognosis." (PMID 39453684, 2024). "Functionally, we identified transcriptomic changes and altered biological pathways caused by NEAT1 isoform imbalance in glioma cells, including the pathway for the regulation of cell migration." (PMID 39032650, 2024). "We characterized alterations of the glioma transcriptome and identified functional molecular pathways caused by altered NEAT1 isoforms." (PMID 39032650, 2024). "Our work has demonstrated that GSC-derived exosomes carry lncRNA NEAT1 to promote the M2 polarization of glioma-associated macrophages (GAMs)." (PMID 39061140, 2024). "NEAT1 overexpression in glioma tissue positively correlates with glioma grade, and reduced NEAT1 expression is associated with longer survival in glioma patients." (PMID 34316694, 2021). "Meanwhile, correlation analysis revealed that expression of NEAT1 was negatively associated with that of miR-128-3p in human glioma tissues." (PMID 34263426, 2021). "Theoretically, there are numerous lncRNAs, such as HOTAIR, H19 and NEAT1, that can be applied as diagnostic and prognostic indicators of glioma." (PMID 34178684, 2021). "Our current study was designed to explore the underlying mechanisms of NEAT1 function in glioma cells." (PMID 33393590, 2021). "We therefore determined the expression of lncRNA NEAT1, which is a core component of paraspeckles and is associated with cancer stem-like cells, in primary glioma cells and ADV-induced tumor spheres by RT-qPCR." (PMID 32843056, 2020). "Previous research has revealed NEAT1 is associated with multiple human cancers, including prostate cancer, hepatocellular carcinoma, glioma and acute promyelocytic leukemia cells." (PMID 29416703, 2018). "Moreover, we demonstrate that recognition and usage of the NEAT1 PAS is a crucial mechanism that regulates NEAT1 isoform biogenesis in glioma under control of the GBM risk factor QKI-5." (PMID 39032650, 2024). "NEAT1 is implicated in the development and progression of brain tumors, particularly gliomas." (PMID 38920691, 2024). "Specifically, a region coinciding with an AluJo- element towards the 3’ end of the non-coding RNA NEAT1, whose expression has been linked to tumor malignancy in glioma, was found to consistently experience less editing in the ADAR3 + condition than in the control condition." (PMID 37784060, 2023). "NEAT1 was shown closely associated with glioma patients’ prognosis." (PMID 35123484, 2022). "In addition, high levels of Lnc NEAT1 are associated with malignant progression in glioma and poor clinical prognosis." (PMID 35850692, 2022). "Long noncoding RNA NEAT1 has been implicated in glioma progression." (PMID 35123484, 2022). "In glioma, NEAT1 expression was elevated and positively associated with the grade of glioma." (PMID 30053878, 2018). "In addition, NEAT1 level was associated with poor prognosis of glioma patients." (PMID 35123484, 2022).
glioma (continued). "For instance, lncRNA NEAT1 enhances the growth and invasiveness of glioma cells by modulating the miR-132/SOX2 axis." (PMID 41050080, 2025). "In this manner, NEAT1 functioned as an inhibitory factor on mTOR, thereby facilitating glioma tumorigenesis through the miR‐185‐5p/DNMT1/mTOR signalling pathway." (PMID 40387409, 2025). "NEAT1 is significantly upregulated, while miR‐185‐5p is downregulated in both glioma tissues and cells." (PMID 40387409, 2025). "Previous study suggested that NEAT1 was upregulated in glioma endothelial cells (CECs), knockdown of NEAT can increased blood-tumor barrier permeability through reducing the expression of TJ related proteins including ZO-1, Occludin, Claudin-5." (PMID 40338929, 2025). "The nuclear-enriched lncRNA NEAT1 has been characterized as an oncogenic driver in gliomas, facilitating glioma stem cell proliferation via the NEAT1/let-7g-5p/MAP3K1 signaling axis." (PMID 41149459, 2025). "The interaction between lncRNA NEAT1 (Nuclear paraspeckle assembly transcript 1) and miR-128-3p that resulted in the sponging of this microRNA contributed not only to glioma pathogenesis, but also to the progression of spinal cord injury-mediated NPP." (PMID 38419943, 2024). "Our study demonstrated that lncRNA NEAT1 targets miR-125a to promote M2 macrophage polarization by directly upregulating STAT3 in glioma." (PMID 39061140, 2024). "Consistently with our previous study, recurring gliomas displayed elevated levels of NEAT1 compared to primary gliomas." (PMID 39453684, 2024). "In summary, our research findings suggest that NEAT1 exhibit elevated expression levels in gliomas, especially in cases that recurred, and TMZ effectively enhances the response of GBM cells to NEAT1 inhibition." (PMID 39453684, 2024). "In human GBM, NEAT1 was reported to be aberrantly upregulated and thought to enhance glioma progression." (PMID 39032650, 2024). "The results showed that recurring gliomas displayed elevated levels of NEAT1 compared to primary gliomas." (PMID 39453684, 2024). "For example, LncRNA NEAT1 regulates pyroptosis in glioma cells and colorectal cancer cells by targeting miR-296-5p or miR-448; while its high expression promotes ferroptosis in non-small cell lung cancer." (PMID 38839842, 2024). "Together, our studies uncovered a novel mechanism that regulates NEAT1 isoforms and their functional impacts on the glioma transcriptome, which affects pathological pathways of glioma, represented by migration." (PMID 39032650, 2024). "Taken together, our study reveals the miR-125a-STAT3 pathway through which exosomal NEAT1 from treatment-resistant GSCs contributes to M2-like macrophage polarization, indicating the potential of exosomal NEAT1 for treating glioma." (PMID 39061140, 2024). "The roles of RBPs involved in glioma tumorigenesis in regulating NEAT1 isoform biogenesis through interacting and modulating the usage of the NEAT1 PAS has not been studied." (PMID 39032650, 2024). "LncRNA nuclear paraspeckle assembly transcript 1 (NEAT1) is involved in tumor cell growth and metabolic reprogramming and is significantly overexpressed in gliomas." (PMID 39272133, 2024). "Overexpression of NEAT1 in gliomas correlates with tumor grade, progression, and patient prognosis, highlighting its potential as a therapeutic target for glioma treatment." (PMID 38920691, 2024). "This study aimed to characterize the function of lncRNA NEAT1 in facilitating the advancement of gliomas." (PMID 39453684, 2024). "Afterward, we searched the CGGA (Chinese Glioma Genome Atlas) database to analyze the levels of NEAT1 in both initial and recurring gliomas." (PMID 39453684, 2024). "We identified QKI recognition element (QRE) sequences located upstream of the human NEAT1 PAS, which are consensus RNA motifs containing ACUAAY-(1–20 nt)-UAAY for the binding of the glial RBP QKI encoded by a glioma risk gene." (PMID 39032650, 2024).